MT-ND4L (mitochondrially encoded NADH:ubiquinone oxidoreductase core subunit 4L)
Description:
Core subunit of the mitochondrial membrane respiratory chain NADH dehydrogenase (Complex I) which catalyzes electron transfer from NADH through the respiratory chain, using ubiquinone as an electron acceptor. Part of the enzyme membrane arm which is embedded in the lipid bilayer and involved in proton translocation.
Synonyms: ND4L; NAD4L; formerly MTND4L
Tractability: Small molecule: an approved drug acts on it; a structure with a bound ligand is known. Antibody: UniProt predicts a signal peptide or a membrane-spanning region.
Gene: Protein-coding gene on chromosome MT (10,470 to 10,766, forward strand). Ensembl gene ENSG00000212907.
Subcellular location: Mitochondrion inner membrane
Subcellular location (Human Protein Atlas): Mitochondria; Centrosome; Cytosol
Pathways (Reactome):
Metabolism of proteins: Mitochondrial translation termination
Gene Ontology:
Molecular function: NADH dehydrogenase (ubiquinone) activity; oxidoreductase activity, acting on NAD(P)H
Biological process: aerobic respiration; mitochondrial electron transport, NADH to ubiquinone; proton motive force-driven mitochondrial ATP synthesis; ATP synthesis coupled electron transport; proton transmembrane transport
Cellular component: mitochondrial inner membrane; mitochondrion; respiratory chain complex I
Gene-disease validity (ClinGen):
ClinGen rates the evidence that MT-ND4L causes each of these diseases.
mitochondrial disease (mitochondrial): Limited.
Homologues: Orthologues: chimpanzee MT-ND4L (99% identical), macaque ND4L (82% identical), pig ND4L (77% identical), rabbit ND4L (77% identical), guinea pig MT-ND4L (70% identical), rat Mt-nd4l (67% identical), mouse mt-Nd4l (66% identical).
Diseases named in the same sentence as MT-ND4L in open-access papers:
MT-ND4L is named in the same sentence as 29 diseases in open-access papers, as found by Europe PMC text mining. Sharing a sentence is not in itself a finding about the gene and the disease. The quoted sentences say what the papers report.
Obesity (3 papers, 2021 to 2022). Accumulation of substantial excess body fat. "The MT-ND4L gene has been associated with obesity and is a mitochondrial encoding subunit of respiratory complex I. In the present study, the missense mutation MT:10609T > C in the MT-ND4L gene was negatively correlated with risk of obesity." (PMID 33659027, 2021). "Furthermore, this study focused on one variant in the MT-ND4L gene, but multiple other (mitochondrial) genes are involved in the energy metabolism and future studies should focus on studying other mitochondrial variants in relation to childhood overweight and obesity." (PMID 36117180, 2022).
Alzheimer disease (1 paper, 2025). A progressive, neurodegenerative disease characterized by loss of function and death of nerve cells in several areas of the brain leading to loss of cognitive function such as memory and language. "Notably, WGCHNA excels in pathogenic gene screening, successfully identifying key genes linked to Alzheimer’s disease (e.g., mt-Nd4l and Cox8b)." (PMID 40255486, 2025).
male infertility (1 paper, 2025). The inability of the male to effect fertilization of an ovum after a specified period of unprotected intercourse. "The current study aimed to investigate the role of single-nucleotide polymorphisms (SNPs) in the MTND3, MTND4L, and MTND4 genes related to both primary and secondary male infertility by comparing their genotypic profiles using Sanger sequencing." (PMID 40843731, 2025). "This study explored the role of single-nucleotide polymorphisms (SNPs) in mitochondrial genes (MT-ND3, MT-ND4L, and MT-ND4) in primary and secondary male infertility." (PMID 40843731, 2025). "This study analyzed the frequency of single-nucleotide polymorphisms (SNPs) in mitochondrial genes (MT-ND4, MT-ND4L, and MT-ND3) and their potential correlation with primary and secondary male infertility." (PMID 40843731, 2025).
mild cognitive impairment (1 paper, 2023). "The mitochondrial coding and non-coding RNA are increased in the circulating extracellular vesicles in AD and mild cognitive impairment (MCI); the AD genes in the category of this study include MT-ND1-4,6, MT-ND4L, MT-ATP6, MT-ATP8, MT-CYB (or MT-CYBT), MT-CO1, and MT-RNR1." (PMID 36982253, 2023).
neuropathy (1 paper, 2024). A disorder affecting the nervous system that manifests with pain, tingling, numbness, and/or muscle weakness. "The mt-Nd3 and mt-Nd4l genes predict the activation of NADH dehydrogenase (ubiquinone) activity in mitochondria, which is associated with mitochondrial function and regulation of neuropathy." (PMID 39796522, 2024).
psoriasis (1 paper, 2025). An autoimmune condition characterized by red, well-delineated plaques with silvery scales that are usually on the extensor surfaces and scalp. "P. clypearia may ameliorate inflammation in psoriasis mice by modulating genes such as Hspa1a, Hspa1b, mt-Nd4l, mt-Nd5, mt-Nd6, Bcl2, Asns, Trib3, and associated pathways related to energy metabolism, cell growth, and apoptosis." (PMID 41385507, 2025). "Our study demonstrated that IMQ downregulated mt-ND4L, mt-ND5, and mt-ND6, while ESW administration could reverse this effect, indicating that ESW may improve psoriasis inflammation by regulating mitochondria and energy metabolism." (PMID 41385507, 2025). "The results indicated that P. clypearia may affect the energy metabolism, cell growth and apoptosis by regulating genes such as Hspa1a, Hspa1b, mt-Nd4l, mt-Nd5, mt-Nd6, Bcl-2, Asns, Trib3, GzmA, CTSG, etc, thereby mitigating psoriasis-related inflammation." (PMID 41385507, 2025).
cancer (6 papers, 2006 to 2024). A tumor composed of atypical neoplastic, often pleomorphic cells that invade other tissues. "Of these 32, several genes (mt-Nd3, mt-Nd4l) involved in mitochondrial metabolism have emerged, as well as other genes such as Epcam and Gprc5c involved in cancer stemness and dormancy of HSCs, respectively, and Cdcp1 that is expressed on leukemic blasts." (PMID 34550965, 2021). "Also among the upregulated genes were mitochondrial protein coding genes (MT-ND3, MT-ND4L, MT-ND4, MT-ND2, MT-CYB, MT-ND1, MT-CO1 etc), which may be as a result of the elevated metabolism characteristic of cancer cells to sustain their survival." (PMID 29132323, 2017).
tumor (2 papers, 2017 to 2019). "Such tumor-exclusive variants were distributed in 13 genes, of which three (MT-ATP8, MT-ND4L and MT-TG) were only observed in this group." (PMID 31673122, 2019). "This notable number of variants that were exclusive to tumor was distributed in 13 genes, of which three (MT-ATP8, MT-ND4L and MT-TG) were only affected in this group." (PMID 31673122, 2019). "Additionally, seven other regions were heteroplasmic only in the tumor (MT-CO2, MT-DLOOP2, MT-ND4L, MT-TC, MT-TK, MT-TM and MT-TT), and there were no genes that were heteroplasmic in the internal control group but not in the tumor group." (PMID 31673122, 2019).
MT-ND4L also shares sentences with these, for which no sentence is quoted: colon cancer (2 papers); infertile (2); Leber hereditary optic neuropathy (2); metabolic disorders (2); amyotrophic lateral sclerosis (1); autistic spectrum disorder (1); cardiomyopathy (1); cataract (1); head and neck tumors (1); Huntington disease (1); infection (1); leprosy (1); MELAS syndrome (1); meningioma (1); metabolic syndrome (1); neurodegenerative disease (1); pancreatic cancers (1); Parkinson disease (1); type 2 diabetes (1); varicocele (1); vascular dementia (1).